BRCA1 (BRCA1 DNA repair associated)
Diseases named in the same sentence as BRCA1 in open-access papers (continued):
Sharing a sentence is not in itself a finding about the gene and the disease.
breast cancer (continued). "Given the increasing emergence of drug resistant breast cancers and the molecular profling already conducted from breast cancer biopsies, the incorporation of BRCA1 status/localization could offer signifcant hope to patients who fail to respond to conventional therapeutics." (PMID 24429466, 2014). "In addition, AKT activation inversely correlates with the BRCA1 expression in human breast cancers." (PMID 25426449, 2014). "Analysis of the BRCA1 and BRCA2 genes in search of mutations in women diagnosed with breast cancer at an early age revealed both BRCA1 and BRCA2 mutations, suggesting that genetic testing for mutations in these genes should be offered to women with early onset breast cancer." (PMID 24678344, 2014). "This suggests that methylated BRCA1 in WBC may also trigger the formation of breast cancer." (PMID 25403427, 2014). "Notably, although the methylation patterns and mRNA expression of DNMT1 showed no significant change in non-BRCA1-mutated breast cancer, the protein expression of DNMT1 is up-regulated." (PMID 24502362, 2014). "Indeed, BRCA1-mutated breast cancers, which are mainly TN tumors, are often compared to non-mutated tumors, is the majority of which are not TNBC, but luminal A, luminal B or HER2+ tumors." (PMID 25416589, 2014). "We previously evaluated the risk of breast cancer among 1,492 women with a strong family history of breast cancer (i.e., two or more breast cancers under the age of 50, or three or more breast cancers at any age), but who tested negative for a BRCA1/2 mutation." (PMID 24667084, 2014). "If specific subsets of BRCA1mut/+ HMECs normally advance beyond the manifestation of an SFR defect to develop additional BRCA1 functional deficiencies accompanied by a much higher risk of tumorigenicity, their selective elimination might suppress subsequent BRCA1 breast cancer development." (PMID 25400221, 2014). "We used cell lines representing the main subtypes of breast cancer to prevent cell line bias: MCF7 as luminal ER-dependent breast cancer, MDA-MB-231 as mesenchymal-like basal breast carcinoma, and MDA-MB-436 as a model of hereditary BRCA1-deficient breast cancer." (PMID 25414831, 2014). "This in turn may yield insights about the etiology of breast cancer in BRCA1 and BRCA2 carriers." (PMID 25919761, 2014). "Moreover, BRCA1 negatively regulates the PI3K/AKT pathway in breast cancer cells." (PMID 25426449, 2014). "Previous studies by the Consortium of Investigators of Modifiers of BRCA1/2 (CIMBA) described the impact of 29 breast cancer susceptibility variants from non-hereditary breast cancer studies on ER-positive and ER-negative breast cancer risk in BRCA1 and BRCA2 carriers." (PMID 25919761, 2014). "This sensitivity is likely not restricted to BRCA1/2-mutated breast cancers, as it is thought that up to 30% of sporadic (germline BRCA wild-type) breast cancers have defects in homologous recombination repair, a phenotype that is often referred to as ‘BRCAness’." (PMID 24887359, 2014). "Indeed, 10–20% of ovarian cancers and ∼20% of breast cancers show inactivation of BRCA1/2." (PMID 25158060, 2014). "Findings from this study will serve to help establish clinical guidelines for the implementation of prevention, counseling, and treatment practices for women who face an elevated risk of breast cancer due to family history, but who do not carry a BRCA1/2 mutation." (PMID 24667084, 2014). "Additionally, as reported, although no BRCA1 staining was observed at the midbody in immunofluorescence slides of cervical cancer cells HeLa, evident localization of BRCA1 was found in the midbody area during cytokinesis in immunoelectron-microscopic sections of breast cancer cells SKBR3." (PMID 24775809, 2014). "Improved breast-cancer specific survival in TNBC BRCA1 mutation carriers compared with non-carriers may be explained by biological differences and/or a higher sensitivity to chemotherapy." (PMID 24348864, 2014).
breast cancer (continued). "Our objective is to test whether a DNA methylation (DNAme) signature derived from BRCA1 mutation carriers is able to predict non-hereditary breast cancer." (PMID 25067956, 2014). "Moreover many sporadic breast cancers also exhibit reduced or diminished expression of BRCA1." (PMID 24962108, 2014). "We report for the first time the identification and characterization of a breast cancer cell line containing a NBN mutation that affects its function, providing a potentially useful cellular model for studying defective NBN protein within a mutant BRCA1 background." (PMID 24928521, 2014). "In the current study, the aim was to investigate if global RNA profiling can be used to identify functional subgroups within breast tumors from families tested negative for BRCA1/2 germline mutations and how these subgroupings relate to different breast cancer patients within the same family." (PMID 24479546, 2014). "Second, although we found some good preliminary evidence that DNAme profiles in buccal cells are better at predicting future breast cancer risk (data not shown), we did not analyse buccal cells from BRCA1 mutation carriers, nor did we have access to independent prospective buccal cell data." (PMID 25067956, 2014). "In addition certain sporadic breast cancers may have hypermethylation of the BRCA1, estrogen receptor (ER), progesterone receptor (PR) and other genes which prevents or lowers their expression." (PMID 25051360, 2014). "However, to our knowledge, the 17q25.3 gain has never before been associated with BRCA1 mutation in breast cancer." (PMID 25416589, 2014). "In addition, BRCA1 down-regulation was shown in a large part of sporadic breast cancer." (PMID 25010005, 2014). "In order to identify sporadic breast cancers sensitive to DSB-inducing agents, many studies have focused on triple-negative (hormone receptor-negative and HER2-negative) breast cancers (TNBCs), as these cluster with BRCA1-mutated breast cancers within the basal-like molecular subtype." (PMID 24887359, 2014). "In this report, we investigated genome-wide RNA profiles of tumors from familial breast cancer cases where no BRCA1 or BRCA2 mutations could be identified by traditional genetic analysis for germline mutations." (PMID 24479546, 2014). "However, no significant methylation differences were observed in the second and third promoters in BRCA1-mutated breast cancer, and in all three promoters in non-mutated breast cancer, compared with normal breast tissues." (PMID 24675476, 2014). "The aim of this pilot study was to develop and evaluate a theoretically grounded and rigorously developed protocol for telephone communication of BRCA1/2 (breast cancer) test results that might be generalizable to genetic testing for other hereditary cancer and noncancer syndromes." (PMID 25355401, 2014). "No similar changes were observed in non-BRCA1-mutated breast cancer (Figure1Aii)." (PMID 24502362, 2014). "Notably, there have only been a few studies on the associations between genetic variants of XRCC4 and breast cancer susceptibility; these studies were performed regardless of the BRCA1/2 status, and the results were inconclusive." (PMID 25360583, 2014). "In this study, we hypothesized that if BRCA1 methylation in WBC reflects an elevated risk for developing breast cancer, WBC from the carriers should exhibit molecular changes similar, to some extent, to those described in BRCA1-methylted WBC from breast cancer patients." (PMID 25403427, 2014). "A recent meta-analysis assessing the prevalence of BRCA1 mutations in TN versus non-TN breast cancer patients from largely high-risk breast cancer populations estimated a risk of 5.65 (95% CI, 4.15 to 7.69) based on analysis of 236 BRCA1 mutation carriers and 2,297 non-carriers." (PMID 25857409, 2014).
breast cancer (continued). "Interestingly, neither any of the epidemiological breast cancer risk factors nor any of the hormones we have analysed in the same serum samples was associated with our BRCA1-mutation DNAme signature." (PMID 25067956, 2014). "Here, familial non-BRCA1/2 tumors clustered with tumors from sporadic and with BRCA germline mutation carriers, indicating that the subgroups of the familial tumors are very similar to the intrinsic molecular subtypes found among sporadic/unselected breast cancers." (PMID 24479546, 2014). "We sequenced all exons and exon-intron boundaries of the SLX4 gene in 738 (270 Jewish and 468 non-Jewish) breast cancer patients with BRCA1/2 mutation-negative breast cancer and a family history of breast cancer with two or more additional affected individuals in the family." (PMID 23840564, 2013). "Interestingly, from clinical and experimental data there is an emerging evidence that familial breast cancers, including BRCA1 and its related forms, could be estrogen-sensitive and interactions between BRCA1 gene expression and estrogens have been reported." (PMID 23533376, 2013). "Although two major breast cancer susceptibility genes, BRCA1 and BRCA2, have been identified accounting for 20% of breast cancer genetic risk, identification of other susceptibility genes accounting for 80% risk remains a challenge due to the complex, multi-factorial nature of breast cancer." (PMID 23967281, 2013). "In addition, since mutations in BRCA1 and BRCA2 were investigated within the locations reported in human breast cancer, cats may carry BRCA1 and BRCA2 mutations in different gene locations." (PMID 24004841, 2013). "The specific defective biological processes that trigger BRCA1/2-associated and -negative tumors remain unclear; whether tumorigenesis in early- and late-onset breast cancer patients differs is also unknown." (PMID 23469205, 2013). "However, in the subset of patients with a germline BRCA1 or BRCA2 mutation who participated in a Phase II study of olaparib monotherapy, no confirmed objective responses were observed in the eight patients with breast cancer." (PMID 24063698, 2013). "Moreover, two different groups recently reported that breast cancers with epigenetically silenced BRCA1 are sensitive to PARPi monotherapy, providing robust evidence to support the use of PARPi in the treatment of selected sporadic BRCA1-inactivated breast cancers." (PMID 24191908, 2013). "Until recently, the process of SV discovery in disease genes like BRCA1 and BRCA2 required gene-specific probes to amplify and quantify the genomic DNA structure and amount, which made it difficult to identify new genes contributing to breast cancer risk though mechanisms such as SV." (PMID 24358278, 2013). "The aim of the current study was to analyze whether female index individuals of breast cancer families who had tested negative for germline mutations in BRCA1/BRCA2 as part of genetic counseling services should be offered mutation testing for PALB2 c.1592delT." (PMID 23941127, 2013). "The present meta-analysis suggested that the BACH1 919Ser polymorphism may decrease the risk of breast cancer among Caucasian populations, particularly in postmenopausal females with a family history of breast cancer and without BRCA1/2 mutations." (PMID 24137204, 2013). "Similarly, sporadic tumors that show deficiencies in BRCA1 tend to be of the basal-like or claudin-low subtype, and estimates indicate that as many as 40% of nonhereditary or sporadic breast cancers show decreased expression of BRCA1." (PMID 23762064, 2013).
breast cancer (continued). "However, in high-risk families, these breast cancer risk factors may be secondary to mutations in the breast cancer associated (BRCA) genes, i.e. BRCA1 and BRCA2." (PMID 23922822, 2013). "Previously reported BRCA2-modifying alleles for breast cancer, including those in FGFR2, TOX3, MAP3K1, LSP1, 2q35, SLC4A7, 5p12, 1p11.2, ZNF365, and 19p13.1 (ER-negative only), are also associated with breast cancer risk in the general population and/or BRCA1 mutation carriers." (PMID 23544012, 2013). "Further subgroup analyses indicated that there were significant correlations between the BACH1 919Ser polymorphism and a decreased risk of breast cancer in postmenopausal females, females with a family history of breast cancer and females without BRCA1/2 mutations." (PMID 24137204, 2013). "Whether BRCA1 may be post-transcriptionally silenced is of particular interest because BRCA1 is frequently downregulated in sporadic breast cancers without associated mutations in the coding or promoter regions." (PMID 24705161, 2013). "Thus it is not surprising that there are data suggesting that a proportion of sporadic basal-like breast cancers may have a dysfunctional BRCA1 pathway, due to gene promoter methylation or transcriptional inactivation." (PMID 23825533, 2013). "Based on our data we cannot determine whether increased PMD in Ashkenazi Jewish women is associated with an increased risk of breast cancer independent of BRCA1 and BRCA2." (PMID 23668689, 2013). "Both the RING and BRCT domains of BRCA1 are of utmost importance for normal BRCA1 function and it is not surprising that a large number of breast cancer predisposing mutations are located in both of these two domains (See Breast Cancer Information Core Data base)." (PMID 24832651, 2013). "BRCA1 function may also be lost in a substantial number of sporadic breast cancers." (PMID 23388117, 2013). "However, an association with specific CtIP/RBBP8 haplotypes has been proposed to be a cancer-risk modifier in breast cancer for BRCA1 mutation carriers, but not for ovarian cancer." (PMID 24403251, 2013). "The study clearly demonstrated that three individuals shared a common haplotype, including the NF1 and BRCA1 loci on chromosome 17 and speculated that the occurrence of NF1 and breast carcinoma in this family was due to the presence of two linked mutations at the NF1 and BRCA1 foci." (PMID 24137429, 2013). "Next, we studied whether BRCA1-IRIS overexpression in no/low BRCA1/p220 expressing cells promotes their survival and hence drug resistance phenotype associated with TN/BL breast cancers." (PMID 22431556, 2012). "As compared to the presence of the variant allele among controls (17.3%), the increased frequency of the KRAS variant was confirmed in breast cancer cases from BRCA1 families (23.5%), but not among breast cancer cases from BRCA2 (13.5%) or non-BRCA1/2 families (15.8%)." (PMID 22436609, 2012). "Although BRCA1 mutation is linked to increased risk of breast cancer and nonphysiological overexpression of BRCA1 induces apoptosis, recent research showed that reduced BRCA1 expression resulted in decreased viability of MDA-MB-231 cells, suggesting functional BRCA1 as a therapeutic target." (PMID 25969759, 2012). "The exact mechanism of the spread of breast cancer to the ovaries had not been elucidated but the risk of primary ovarian cancer is increased in women with breast-ovarian cancer syndrome (BRCA1/2 mutation), lymphoma had been reported to spread to the ovaries but there was none in our series." (PMID 22759383, 2012).
breast cancer (continued). "BRCA1/2 mutations for non-familial Korean breast cancer patients were detected at a high rate, particularly, in patients with early onset of less than 35 years of age, bilateral breast cancer, and breast and ovarian cancer." (PMID 22382806, 2012). "BRCA1-defective human breast cancer, HCC1937 cells (a BRCA1 mutation with an insertion of C at nucleotide 5382, and a negative expression of HER2/neu, and estrogen receptor α (ERα)) were significantly more sensitive to cisplatin than BRCA1 reconstituted cells with a full-length cDNA transfection." (PMID 23203101, 2012). "Thus, interruption of the BRCA1-EGFR complex may be one possible mechanism by which lapatinib attenuates DNA repair in breast cancer cells." (PMID 23071597, 2012). "Women recently diagnosed with breast cancer may want to take their BRCA1/2 status into consideration for their choice of surgical treatment (i.e. breast-conserving with radiotherapy versus ipsi/contralateral mastectomy) and, in the near future, chemotherapy (i.e. PARP-inhibitors)." (PMID 22569005, 2012). "BRCA1 methylation is more common in relatively young, premenopausal women, which could explain the higher incidence in female breast cancer since the male breast cancer patients were significantly older than the female breast cancer patients." (PMID 22765268, 2012). "For example, between 30-50% of women with a BRCA1/2 mutation have no significant or known family history of breast or ovarian cancer and up to 8% of women with Ashkenazi Jewish ancestry and breast cancer diagnosed under 50 years have no relevant family history." (PMID 22838957, 2012). "That a marker of a differentiated normal mammary epithelial cell could enrich for cells with TIC activity in the context of breast cancer is also supported by recent evidence from multiple laboratories that, in BRCA1 basal-like tumors, the TIC population arises from the luminal lineage." (PMID 22225988, 2012). "Since the initial discovery of BRCA1 and its role in the cellular DNA damage response, the last few years have witnessed a broad expansion in the number of interacting protein partners, the cellular localization sites, and the functions of this critical breast cancer regulatory protein." (PMID 24278741, 2012). "This improvement, although not statistically significant, is nevertheless plausible, as extended family history captures all of the many breast cancer genetic risk factors in addition to BRCA1/2 mutations as well as nongenetic shared familiar environmental factors not captured in the model." (PMID 23127309, 2012). "Therefore, while MMTV-Luc2 mice appear relevant for imaging of other MMTV-driven oncogenic model systems, as exemplified by the MMTVPyVT model in this work, the applicability of MMTV-Luc2 imaging in basal-type breast cancer models (such as BRCA1-knockout mice) is yet to be studied." (PMID 22646761, 2012). "Consequently, the poor uptake of existing breast cancer prevention options, which appears to be more marked in those with BRCA1 compared to BRCA2, serves to illustrate the urgent need to identify other agents for breast cancer prevention in this high-risk group." (PMID 26097796, 2012). "Recent large population base case-control study in a Chinese population and large study in a Polish population without BRCA1 mutation could not demonstrate the association between 936C/T polymorphisms and breast cancer risk." (PMID 23203097, 2012). "Notably, it has been reported that heterozygosity of BRCA1 may result in abnormal self-renewal of breast cancer stem cells." (PMID 22405187, 2012). "There was no BRCA1 mutation detected among 17 male breast cancer patients." (PMID 22382806, 2012). "However, mammographic density has also been shown to modify the breast cancer risk for BRCA1 carriers, which also makes the absence of association for rs10995190 in BRCA1 carriers somewhat surprising." (PMID 22348646, 2012).